IL17A (interleukin 17A)
Diseases named in the same sentence as IL17A in open-access papers (continued):
Sharing a sentence is not in itself a finding about the gene and the disease.
enthesitis (53 papers, 2013 to 2025). Inflammation at the site of insertion of ligaments, tendons, and other fibrous structures into bone. "The variables represented by enthesitis and dactylitis or cardiovascular risk complications, instead, orient towards treatment with anti-IL-17A antibodies." (PMID 40863428, 2025). "IL-17, a group of pro-inflammatory cytokines comprising six known members (IL-17 A/B/C/D/E/F), is mainly generated by Th17 T cells, and its presence has been associated with the development of psoriatic skin lesions and enthesitis." (PMID 37511421, 2023). "IL-23 overexpression in mice causes a florid enthesitis which is driven by enthesis resident population of IL-23R positive innate T-cells that drove IL-17A dependent pathology." (PMID 30505307, 2018). "The anti-IL-17A secukinumab was prescribed in 12% of SpA, of which 71% had enthesitis and dactylitis (14 pt)." (PMID 40863428, 2025). "In enthesitis, IL-17A is expressed by immune cells and is thought to augment the injury-induced inflammation through the release of cytokines and other mediators by stromal cells, which in turn trigger neutrophil migration and activation." (PMID 39988349, 2025). "X-ray and histological analyses showed that enthesitis, bone destruction and new bone formation were inhibited by the IL17A vaccine." (PMID 36737108, 2023). "IL-17A induces enthesitis by promoting osteoclast formation, but its effect on osteoblast differentiation varies depending on the cell type, the differentiation stage of a cell, and the timing and duration of exposure." (PMID 37893130, 2023). "It has been reported that mice overexpressing IL-23 developed enthesitis and peripheral arthritis, through T-helper 17 (Th17) cells activation and production of IL-17A, IL-22, and IL-17F." (PMID 36308677, 2023). "Anyway, clinical evidence shows that IL-23 blockade is less effective than inhibition of IL-17A on improving disease symptoms in the spine, suggesting potential differences between the role of IL-23 in spinal versus peripheral enthesitis." (PMID 36308677, 2023). "First, IL-17A blockers have proven efficacy for both peripheral and axial SpA including evidence for efficacy for isolated enthesitis as a secondary outcome measure." (PMID 33815371, 2021). "Blocking IL-22 in SKG mice for 8 weeks from the first moment of clinical manifestations reduced Achilles tendon enthesitis, similar to the reduced severity of enthesitis observed in the IL-17A-/- SKG mice." (PMID 34267743, 2021). "In SKG mice that developed a SpA disease after microbial antigen injection, IL-22 together with IL-17A have been shown to promote peripheral enthesitis." (PMID 30057583, 2018). "Ixekizumab, a second IL-17A blocker with a 50-fold higher affinity, showed efficacy for enthesitis in the P-SPIRIT-1 study." (PMID 29846815, 2018). "In addition to IL-17A, IL-22, as a downstream cytokine of IL-23, was shown to be relevant for the severity of enthesitis in both the IL-23mc and SKG mice model." (PMID 34267743, 2021). "This supports the hypothesis that IL-17A inhibition may prevent the development of new enthesitis sites as well as providing sustained resolution of enthesitis in patients with baseline enthesitis." (PMID 31801620, 2019). "Secukinumab a IL-17A blocker has shown efficacy for enthesitis in several trials." (PMID 29846815, 2018). "Collectively, our findings indicate that augmented IL-17A in PsA dermatitis induces the elevation of FGF7 levels in joint enthesis and results in a non-redundant role of FGF7 signaling in the development of ankylosing enthesitis in PsA." (PMID 39919800, 2025). "Further support for the role of the TH17 axis comes from DBA/1 mice, which spontaneously develop AS‐like enthesitis but do not do so when IL‐17A is neutralized with antibodies." (PMID 32696457, 2020).
enthesitis (continued). "Key amongst these is whether spinal inflammation may exhibit entheseal IL-17A production independent of IL-23 but peripheral enthesitis is largely dependent on IL-23 driven IL-17 production." (PMID 33815371, 2021).
non-small cell lung carcinoma (52 papers, 2014 to 2025). A group of at least three distinct histological types of lung cancer, including non-small cell squamous cell carcinoma, adenocarcinoma, and large cell carcinoma. "Recent studies show that IL-17A overexpression has tumorigenic activities in non-small cell lung cancer (NSCLC) in mice and it is associated with genomic instability in bronchial epithelial cells from the lung tissue of smokers and non-smokers." (PMID 38999871, 2024). "This study identifies circulating interleukins—particularly IL-1RA, IL-6, IL-8, IL-10, and IL-17A—as promising blood-based biomarkers for the early detection of non-small cell lung cancer (NSCLC)." (PMID 41303495, 2025). "In this context, the targeting of IL-17A is seemingly efficacious in the experimental immunotherapy of colorectal, breast and non-small cell lung cancers in murine models." (PMID 32244751, 2020). "Considering the established roles of Interleukin (IL)-6 and IL-17A in non-small cell lung cancer (NSCLC) progression and immune evasion, we developed a combination strategy integrating cytokine neutralization with CTT (combination therapy) in LLC1 tumor-bearing mice." (PMID 41084279, 2025). "Likewise, in non-small-cell lung cancer, IL-17A enhances ROS production and activates NRF2, resulting in p62 accumulation and a suppressive TME." (PMID 41291343, 2025). "IL-17A expression was inhibited in A549 non-small cell lung cancer cells using RNA interference." (PMID 38394046, 2024). "IL-17A also stimulates the production of VEGF by cancer cells via the STAT3/GIV signaling pathway, promoting angiogenesis in non-small-cell lung cancer." (PMID 39906741, 2024). "A significant finding is that IL-17A can influence tumor growth and angiogenesis in non-small cell lung cancer despite not affecting VEGFA production." (PMID 38515019, 2024). "Similarly, IL-17A strongly stimulates VEGF production and drives neovascular growth in animals via the STAT3/GIV signaling pathways in non-small-cell lung cancer." (PMID 36873773, 2023).
co-infection (51 papers, 2009 to 2025). "While the loss of IL-17A producing lymphocytes promotes disease severity in simian immunodeficiency virus and Cryptosporidium co-infection a protective role of IL-17A against Cryptosporidium remains undefined." (PMID 27467505, 2016). "We showed that if IL-1β, TNFα and OSM were present in uninfected excisional skin lesions, IL-17A, IL-17F and IL-22 were specifically produced after S. aureus and P. aeruginosa co-infection of the lesions." (PMID 36275755, 2022). "These responses are of interest in HIV/HCV coinfection due to the role of virus-specific IL-21-production in the enhancement of viral clearance and the pro-fibrogenic properties of IL-17A." (PMID 27124305, 2016). "Coinfection results in differential cytokine profiles, with increased levels of IFN-γ+IL-17+CD4+ and IFN-γ+IL-17-CD8+ cells, and altered levels of cytokines such as IL-17A and MCP-1, which are associated with higher bacterial loads in TB patients." (PMID 40217604, 2025). "How HIV/TB co-infection effects on the IL-17A-secreting CD8+ T cells need further investigation." (PMID 37483385, 2023). "Excluding co-infection with soil-transmitted helminths, individuals with C. sinensis still had significantly higher antigen-specific IgG and IgE levels, and diminished serum levels of IL-1β, IL-2, IL-4, IL-12p70, IL-17A, IFN-γ and TNF-α." (PMID 36083861, 2022). "In contrast, co-infection with Hh promoted Hp-induced gastric disease at 6 months post-Hp inoculation (MPI) but not at 11 MPI which was correlated with enhanced transcription of gastric Il-17A." (PMID 33255175, 2020). "perfringens co-infection, while only IL-17A transcripts were increased in the spleen." (PMID 29599973, 2018). "In addition, the diminished systemic production of IL-2, IL-17A and IL-17F also indicate a more extensive impairment in Th1 and Th17 responses in co-infection settings." (PMID 25211342, 2014). "Comparable severity of cecal pathology between Hh+Hp and mono-Hh mice was in agreement with the finding that co-infection with Hp did not significantly enhance cecal transcription of key ILCs 1/3-associated genes including Ifnγ, Tnfα, Il-1β, and Il-17A at 21 WPI." (PMID 33255175, 2020). "In contrast, this co-infection in RAG2 females downregulated expression of several cytokines such as Il-1β, Il-17A, Ifnγ, Tnfα, and Il-13 only at 10 WPI, but increased transcription of colonic Il-22 at 21 WPI." (PMID 33255175, 2020). "In addition, the presence of more IL-17A-producing γδ and non-γδ T cells in early lesions (1–7 days), and L. major antigen-responsive Th17 cells after 28 days of coinfection, with a corresponding increase in IL-1β, may recruit more naïve neutrophils into the inflammatory site." (PMID 31107882, 2019). "Chemokines and IL-17A are significantly upregulated during isolated candidemia compared to controls but do not distinguish it from bacterial co-infection." (PMID 41229429, 2025). "Nonetheless, neither chemokines nor IL-17A appeared to differentiate between bacterial/fungal co-infection and isolated candidemia." (PMID 41229429, 2025). "The anti-IL-17A data suggest that IL-17A is partially responsible for the lesion exacerbation that occurs during coinfection, but this does not exclude a contribution of other immune mediators and bacterial or parasitic factors to the development of disease." (PMID 31107882, 2019). "To examine the immune profile of individuals with co-infection, we compared the concentration of 15 immune markers (IL-1β, IL-6, IL-8, TNF-α, IL-7, G-CSF, MCP-1/CCL2, MIP-1-α/CCL3, IL-12, IFN-γ, IL-13, IL-17A, GM-CSF, IL-10, and TGF-β1) among the three groups using Kruskal-Wallis ANOVA." (PMID 27128316, 2016). "We compared peripheral HCV-specific IL-21 and IL-17A-producing T cell responses with a well-established marker of liver progression, the Fibrotest, as well as LPS levels, a marker of microbial translocation in those with chronic HCV/HIV coinfection." (PMID 27124305, 2016).
co-infection (continued). "Those with Plasmodium mono-infection had higher levels of IL-4, IL-6, IL-10, IL-12, IL-13, IL-17A, IFN-γ, and MIP1-α/CCL3 compared with DENV mono-infection or co-infection; those with Plasmodium mono-infection had more cough than those with DENV mono-infection." (PMID 27128316, 2016). "Since Th17 cells have the ability to produce both IL-21 and IL-17A, and considering the fact that IL-21 has a known role in viral control, it raises the question of whether these cytokines are produced in an antigen-specific manner in HIV/HCV coinfection." (PMID 27124305, 2016). "The reason for the differential role of IL-17A in the two studies is not clear but it is notable that the Zimmerman study was performed in the presence of co-infection with SFB and Hh, and this strong inflammatory drive may alter the pathophysiological role of particular cytokines." (PMID 27193261, 2016). "The top three markers contributing most to overall network density by AUC in the subgroup of those without HIV-1 co-infection were CXCL10, C-reactive protein, and IFNα2, whereas the top three markers in the subgroup of those with HIV-1 co-infection were IL-17A, IL-1β, and TNFα." (PMID 34386782, 2021). "Interestingly, non-HIV patients with co-infection and pneumocystosis alone showed lower levels of SP-A, IL-1β, TNF-α, IFN-γ, IL-18, IL-17A, and IL-23 than histoplasmosis patients, suggesting an immunomodulatory ability of P. jirovecii over H. capsulatum response." (PMID 34829225, 2021).
glioma (49 papers, 2010 to 2025). A benign or malignant brain and spinal cord tumor that arises from glial cells (astrocytes, oligodendrocytes, ependymal cells). "Their investigation delved into the systemic ramifications of disrupted IL‐17A/IL‐17RA signaling in the intestine, targeting both pancreatic and syngeneic murine glioma (GBM) tumors." (PMID 38585232, 2024). "Building on the unexpected outcomes of global IL‐17RA deficiency, Chandra and colleagues then explored the systemic impact of disrupted IL‐17A/IL‐17RA signaling in the intestine, focusing on both pancreatic and syngeneic murine glioma (GBM) tumors." (PMID 38585232, 2024). "The results showed that mRNA expression of IL‐17A was significantly higher in WHO IV grade glioma tissues than that in WHO I‐II grade group." (PMID 30353649, 2019). "Here, we investigated the migration and invasion abilities in human GBM cell lines and found that IL‐17A promoted migration and invasiveness of U251 and U87 glioma cell lines, similar to previous reports." (PMID 30353649, 2019). "The results showed that IL‐17A‐positive staining was significantly increased in WHO III‐IV glioma tissues compared to that in WHO I‐II glioma tissues and Adjacent tissues (**P < 0.01)." (PMID 30353649, 2019). "This study confirmed the presence of the Th17 cytokine, IL-17A, and identified the presence of Th17 cells in both human and mouse glioma." (PMID 21060663, 2010). "Collectively, the data indicate that Th17 are present in human glioma and that the expression of the Th17 cytokine, IL-17A, as well as the number of T cells, is increased in oligodendroglioma and GBM, compared to low-grade astrocytoma." (PMID 21060663, 2010). "The presence of IL-17A mRNA in human glioma was recently identified through a large scale microarray analysis of Th1-, Th2- and Th17-related genes." (PMID 21060663, 2010). "In this report, we demonstrate that mRNA expression for the Th17 cell cytokine IL-17A, as well as Th17 cells, are present in human glioma." (PMID 21060663, 2010). "The mRNA expression for IL-17A in glioma was recapitulated in an immunocompetent mouse model of malignant glioma." (PMID 21060663, 2010). "In a similar way, it has been suggested that even IL-17A might control glioma cell invasiveness by inducing the overexpression of MMP-9/-2 via PI3K/AKT." (PMID 36980765, 2023). "To confirm it, we treated glioma cells with IL‐17A (5 ng/mL) in a time course pattern." (PMID 30353649, 2019). "In opposition, IL-17A has been reported to promote tumor growth either indirectly via the production of other pro inflammatory cytokines by immune cells, or directly via stimulation of tumor stem cells in glioma models." (PMID 30518157, 2018). "In future investigations, we intend to identify whether IL-17A expression in glioma is solely a CD4+ T cell cytokine or if B cells also produce this cytokine through analysis of IL-17A mRNA levels in CD4 T cell- and B cell-deficient mice with malignant glioma." (PMID 21060663, 2010). "Importantly, mRNA expression for the Th17 cytokine, IL-17A, is increased in human glioma relative to normal human brain and Th17 cells are present in GBM." (PMID 21060663, 2010). "Importantly, we could not detect mRNA for the Th17-secreted cytokine, IL-17A, in Rag1−/− mice with glioma, suggesting that T or B cells are required for IL-17A expression." (PMID 21060663, 2010). "Various inflammatory cytokines, including TNF, CSF2, IL1A, IL17A, IL6, and IFNG, were predictively inhibited in glioma samples exhibiting high CSMD1 expression." (PMID 38561856, 2024). "In vivo, the presence of Th17 lymphocytes and IL-17A mRNA was demonstrated in glioma from mouse and human yet without assessing their impact in that situation." (PMID 27589729, 2016). "We report that mRNA for the Th17 cytokine, IL-17A, is expressed in immunocompetent mice with glioma, but not in Rag1−/− immunodeficient mice with glioma." (PMID 21060663, 2010).
glioma (continued). "However, IL-17A expression appears to be dependent on T cell accumulation, since IL-17A mRNA levels were not different between types of human glioma, when normalized to CD3ε mRNA levels." (PMID 21060663, 2010). "However, IL-17A mRNA is detectable in glioma of WT mice, but not in glioma of Rag1−/− mice." (PMID 21060663, 2010).
Hepatic steatosis (49 papers, 2013 to 2025). Steatosis is a term used to denote lipid accumulation within hepatocytes. "The exacerbated hepatic steatosis produced by IL-17A is caused by inhibiting fatty acid β-oxidation and promoting TG accumulation." (PMID 40977717, 2025). "Mice with deficiency of IL-17A, IL-17F or their receptor IL-17RA exhibit attenuated liver steatosis and injury." (PMID 36457551, 2022). "In an analysis using mice, IL-17A-, IL-17F-, and IL-17RA-deficient mice showed liver steatosis in a fatty liver model due to a methionine choline-deficient diet, but the degree of liver dysfunction was significantly lower than that of wild-type mice." (PMID 33918456, 2021). "Th17 cells and the expression of IL-17a were positively associated with human fatty liver-associated HCC." (PMID 34869507, 2021). "In addition, the implication of Th17 cells and the production of IL-17 has been reported in multiple studies both in patients and mice, and its pathogenic role has been proved by inhibition of IL-17A/IL-17AR signaling, which protected mice from diet-induced liver steatosis and liver injury." (PMID 35052726, 2021). "IL-17A plays a role in chronic low-grade inflammation, facilitating the progression from hepatic steatosis to MASH and liver fibrosis." (PMID 40977717, 2025). "IL17A has been shown to exacerbate hepatic steatosis and inflammation, contributing to the progression of MASH through pathways such as ERK1/2/p65 signaling, which promotes hepatocyte apoptosis." (PMID 39459627, 2024). "As a tumor-promoting cytokine, IL-17A can regulate alcohol-induced hepatic steatosis, inflammation, fibrosis and HCC, and the development of HCC in alcohol-fed mice was suppressed by deleting the IL-17RA gene." (PMID 36998605, 2023). "IL-17A also appears to be involved in the development of fatty liver disease, with evidence suggesting that the IL-17 axis plays a crucial role in the pathogenesis of steatohepatitis and progression to fibrosis." (PMID 37533855, 2023). "Digoxin, for example, has been reported to inhibit the secretion of IL-17A, reduce the levels of liver steatosis, and block the infiltration of liver immune cells, thus preventing liver injury." (PMID 34616724, 2021). "Our data showed that FPC diet intake induced hepatic steatosis and inflammation in the liver and brain along with elevated RORγ and IL-17A signaling." (PMID 33292701, 2020). "However, IL-17A blockade led to significantly improved whole-body insulin sensitivity, and it reduced hepatic steatosis and LD diameter to levels comparable with CD11cWT littermates." (PMID 37140993, 2023). "Moreover, multiple experimental murine and in vitro models showed that IL-17A administration can lead to an increase in hepatic steatosis." (PMID 34463867, 2021). "However, despite these similarities, MCDD-fed IL-17RA-/-, IL-17A-/- and IL-17F-/- mice exhibited increased levels of hepatic steatosis compared to WT mice, as determined by hepatic triglyceride deposition." (PMID 26895034, 2016). "Our study aims to examine the connection between the plasma levels of IL-17A/F and TLR4 and the extent of hepatic steatosis, as well as the likelihood of fibrosis in patients with MASLD." (PMID 39335657, 2024). "Simultaneous blocking of CD25 or IL-17A and IL-17F shifted the TH17/Foxp3+ TREG imbalance from MCD diet-induced TH17 dominance to Foxp3+ TREG dominance and also decreased hepatic steatosis and inflammation." (PMID 34463867, 2021). "Accordingly, we observed elevated IL-17A–expressing CD4+ T cells in the livers of obese mice lacking LKB1 in DCs, a feature that was associated with enhanced hepatic steatosis." (PMID 37140993, 2023). "Using therapeutic strategies targeting the IL-17A pathway and drugs that prevent the progression from MASLD to MASH, such as polyunsaturated phosphatidylcholine (PPC) and 3’,3’-diidolylmethane (DIM), restored the immune balance Th17/Treg reducing liver inflammation and the hepatic steatosis." (PMID 40977717, 2025).